TMEM174 (transmembrane protein 174)
Description:
Regulator of plasma phosphate homeostasis. Decreases serum inorganic phosphate (Pi) uptake by regulating the sodium-phosphate cotransporter SLC34A1 trafficking by PTH and FGF23 in the kidney.
Synonyms: MGC13034; FLJ31268
Tractability: Antibody: UniProt places it where antibodies can reach, with high confidence; UniProt predicts a signal peptide or a membrane-spanning region; its Gene Ontology location is reachable by antibodies, with medium confidence.
Gene: Protein-coding gene on chromosome 5 (73,173,193 to 73,175,143, forward strand). Ensembl gene ENSG00000164325.
Subcellular location: Endoplasmic reticulum membrane; Apical cell membrane
Gene Ontology:
Molecular function: protein binding
Biological process: phosphate ion homeostasis
Cellular component: apical plasma membrane; endoplasmic reticulum membrane
Genetic constraint (gnomAD): Loss-of-function variants: 14 observed, 17.79 expected, observed/expected ratio (o/e) 0.79, 90% interval 0.52 to 1.23. The upper end of that interval is the gene's LOEUF score, 1.23, which puts it in group 5 of 6, group 1 being the genes least tolerant of losing a copy. Missense variants: 321 observed, 315.96 expected, observed/expected ratio (o/e) 1.02, 90% interval 0.93 to 1.11. Synonymous variants: 130 observed, 128.47 expected, observed/expected ratio (o/e) 1.01, 90% interval 0.88 to 1.17.
Homologues: Orthologues: chimpanzee TMEM174 (99% identical), macaque TMEM174 (95% identical), pig TMEM174 (83% identical), mouse Tmem174 (81% identical), guinea pig TMEM174 (81% identical), rat Tmem174 (80% identical), rabbit TMEM174 (77% identical), dog TMEM174 (72% identical), zebrafish tmem174 (49% identical), tropical clawed frog tmem174.2 (44% identical).
Diseases named in the same sentence as TMEM174 in open-access papers:
TMEM174 is named in the same sentence as 12 diseases in open-access papers, as found by Europe PMC text mining. Sharing a sentence is not in itself a finding about the gene and the disease. The quoted sentences say what the papers report.
renal carcinoma (2 papers, 2013 to 2014). A carcinoma arising from the epithelium of the renal parenchyma or the renal pelvis. "Our previous study demonstrated high TMEM174 expression in the kidney and also revealed its potential involvement with renal cancer based on its capacity to stimulate cell proliferation." (PMID 25202393, 2014). "Our previous study demonstrated high expression of TMEM174 in the kidney and its potential involvement in renal cancer based on its capacity to stimulate cell proliferation." (PMID 24223660, 2013). "However, the expression of TMEM174 in renal cancer and normal renal tissues remains to be elucidated." (PMID 25202393, 2014). "In conclusion, the TMEM174 gene exhibited high expression levels in certain renal carcinomas, which may indicate that TMEM174 may have a significant role in the development and progression of these renal carcinomas." (PMID 25202393, 2014).
hyperphosphatemia (1 paper, 2022). Abnormally high level of phosphate in the blood. "Furthermore, a dietary Pi load causes marked hyperphosphatemia and abnormal NaPi2a regulation in Tmem174-KO mice." (PMID 35428804, 2022). "AKI-Tmem174−/− mice, however, had significantly higher levels of plasma Pi at 24 h after FA administration compared with AKI- Tmem174+/+ mice, and the hyperphosphatemia was maintained only in Tmem174−/− mice until 7 days after FA treatment." (PMID 35428804, 2022). "Thus, Tmem174, a strongly correlated molecule with NaPi2a in the GCNs, is thought to be involved in the regulation of NaPi2a by PTH and FGF23 in the kidney and the prevention of hyperphosphatemia in response to a high dietary Pi load." (PMID 35428804, 2022).
hypophosphatemia (1 paper, 2022). Lower than normal levels of phosphates in the circulating blood. "On the other hand, Tmem174−/− mice did not exhibit the abnormal bone morphology seen in Hyp mice and we speculate that this is because Tmem174−/− mice do not develop hypophosphatemia." (PMID 35428804, 2022).
pyelonephritis (1 paper, 2013). An inflammatory process affecting the kidney. "Therefore, TMEM174 is suggested to be involved in the regulation of pyelonephritis via CREB." (PMID 24223660, 2013).
cancer (1 paper, 2013). A tumor composed of atypical neoplastic, often pleomorphic cells that invade other tissues. "Thus, CREB is suggested to be an important transcription factor involved in the regulation of TMEM174 gene expression, and the inhibition of CREB, and possibly AP-1, is suggested to inhibit the migration and invasion of cancer cells." (PMID 24223660, 2013).
TMEM174 also shares sentences with these, for which no sentence is quoted: papillary renal cell carcinoma (2 papers); squamous cell carcinoma (2); transitional cell carcinoma (2); adrenal gland (1); clear cell carcinoma (1); interstitial nephritis (1); undifferentiated carcinoma (1).